IGF2 (insulin like growth factor 2)
Diseases named in the same sentence as IGF2 in open-access papers (continued):
Sharing a sentence is not in itself a finding about the gene and the disease.
cancer (continued). "In summary, a series of DNA methylation surveys revealed that a relatively large fraction of imprinted genes are epigenetically affected in human cancers, and also that this epigenetic instability is particularly pronounced in a subset of imprinted genes, such as PEG3, IGF2, DLK1, MEST and GNAS." (PMID 26338779, 2015). "IGF-1 may stimulate cancer angiogenesis in part by upregulating vascular endothelial growth factor (VEGF) expression, whereas IGFs (IGF-1 and IGF-2) promote vasculogenesis in embryonic stem cells through the upregulation of VEGF." (PMID 24765205, 2014). "This review summarises the critical discussion at an international workshop held under the auspices of The European Network for Cancer Research in Children and Adolescents (ENCCA) consortium, where the potential for drug development to target IGF2 and the WT epigenome was debated." (PMID 25478630, 2014). "Altogether, these data indicate that there is no major phenotypic difference between the IGF2-low and IGF2-high carcinoma in terms of clinical, histological and molecular markers." (PMID 25089899, 2014). "Carcinomas that developed with low frequency in ΔCat mice never showed spontaneous overexpression of Igf2 (14 and unpublished observations)." (PMID 22952916, 2012). "We conclude that only a limited set of imprinted genes, including IGF2 and SNRPN, may be useful for LOI cancer biomarker studies." (PMID 21042416, 2010). "As an example, IGF2 protein expression is clearly elevated in senescent cancer cells in vitro, but the expression of IGF2 protein does not quantitatively differ in vivo, when senescent and proliferating cells are compared (data not shown)." (PMID 18349844, 2008). "This expression pattern underpins the hypothesis that BORIS is the key regulator establishing the male germline imprint of IGF2, that it acts antagonistically to CTCF and defines its inclusion within the cancer-testis group of genes." (PMID 18769711, 2008). "Our results show that none of the growth factors measured (IGF1, IGF2 or IGFBP3) have any value in cancer screening in men." (PMID 16804529, 2006). "We therefore are confident that the general conclusion that none of the growth factors measured (IGF1, IGF2 or IGFBP3) have any value in cancer screening can be extended to all the main cancers in men and women." (PMID 16804529, 2006). "As described for IGF2/H19, epigenetic changes at DLK1/GTL2 occur in human cancers." (PMID 15798773, 2005). "Despite the intensive studies on the role of IGF2 in cancer, whether IGF2 is responsible for the activation of CAFs is not elucidated." (PMID 39759028, 2024). "Additionally, the neutralization of IGF2 did not affect viral replication or propagation in all cancer cells tested in vitro." (PMID 38853689, 2024). "On the contrary, other evidence demonstrates that cancer treatment might negatively affect CAFs by enhancing their secretion of IGF1/IGF2, with a negative impact on cancer progression." (PMID 38892104, 2024). "Indeed, a number of studies have shown a predominant activation of IGF2 fetal promoters (p2–p4) in a variety of cancers displaying IGF2 increased expression levels, with variable uncoupling of DMR0–2 methylation, along with monoallelic IGF2 and/or H19 expression." (PMID 37371750, 2023). "Thus, as was previously reported in cancer cells with LOI, CTCF-orchestrated intrachromosomal looping may be essential for maintaining normal imprinting of IGF2 in decidual tissues." (PMID 36231092, 2022). "Moreover, several studies have confirmed that lncRNA Neat1 could sponge miR-185-5p to regulate IGF2 expression or DNMT1/mTOR signaling, promoting cancer progression." (PMID 35501920, 2022). "IGF-2 also binds to IGF-1R and may lead to cancer cell proliferation in HCC patients." (PMID 33669204, 2021).
cancer (continued). "Insulin-like growth factor 2 mRNA-binding proteins (IGF2BPs; IGF2BP1/2/3), as a newly discovered m6A regulator in recent years, promotes the stability and storage of its target mRNA (such as MYC) in an m6A-dependent manner, and has a carcinogenic effect in cancer." (PMID 34206803, 2021). "Collectively, these data support the notion that IGF2 might not be the major mediator of IGF2BP1-modulated oncogenic effects in cancer." (PMID 33673232, 2021). "Interestingly, our data highlighted that PDE4D silencing may affect the gene expression of several cancer-related genes in all HCC cell lines, among which emerged IGF2." (PMID 34062786, 2021). "On general, we perform this study to deep explore the role of IGF2 in CRC stem cells autophagy and its regulation in the maintenance of CSC characteristics hoping to get a better understanding of regulatory factors and their molecular mechanisms in CRC cancer stem cells regulation." (PMID 33173015, 2020). "Insulin, insulin-like growth factor-1 (IGF-1), and insulin-like growth factor-2 (IGF-2) are ligands for the transmembrane tyrosine kinase receptors, insulin receptor (IR), and IGF-1 receptor (IGF-1R), which have important roles in growth, development, cancer, and metabolic disease." (PMID 33604295, 2020). "Moreover, activation of several FGF downstream signaling pathways was also observed including cancer related pathways (RAS-MAPK, PIK3-AKT, and STAT) with a significant upregulation of several key molecules in these pathways (e.g., BIRC5, RAF1, MYCN, IGF2, SNAI2, POSTN)." (PMID 31477684, 2019). "Furthermore, because IGF-2 has high affinity to IR-A, the IGF-2 produced by cancer cells may exert an autocrine/paracrine effect by binding to IR-A and promote cancer cell proliferation." (PMID 31354621, 2019). "Moreover, poorly-differentiated cancer thyrospheres produce a high amount of both IGF-1 and IGF-2." (PMID 30513575, 2018). "Moreover, LOI of IGF2 is not exclusive to cancer cells, it is also commonly observed in normal neonates and adult humans." (PMID 28521298, 2017). "Moreover, activation of IGF-2/INSR-A loop promotes invasion and metastasis in choriocarcinoma, while downregulating of INSRs reduces cell proliferation, angiogenesis, and metastasis in cancer cells both in vitro and in vivo." (PMID 26217584, 2015). "IGF2 status is clearly correlated with malignancy, but it is not a prognostic marker in carcinoma." (PMID 25089899, 2014). "Findings from the realm of cancer biology suggest that apart from its role in transcriptional regulation alongside its host gene IGF-2, miR-483-3p may also engage in independent regulation through the WNT/β-catenin signaling pathway, distinct from IGF-2 transcriptional control." (PMID 38972889, 2024). "Furthermore, we aimed to extend our previous investigation and compare levels of IGF-1, IGF-2, PAPP-A, PAPP-A2, STC1, and STC2 in corresponding ascites and serum samples, providing new insights into the mechanisms behind IGF-mediated tumorigenicity and cancer biology." (PMID 38396692, 2024). "This parallel increase in IGF2 transcription, coupled with defective cancer processing, generates the known high-molecular IGF-II pro-hormone variants, which are refractive to IGFBP-3 (and SpI2-6/IGF2R) binding but not to the IGF-II RTKs (IGF-IR and IRA) which are efficiently activated." (PMID 38255147, 2023). "Moreover, EVs can affect receptor cell function, and dormant cancer cell-derived EVs promote PMN formation and cancer cell survival in the bone marrow by reprogramming the metabolic processes of bone marrow mesenchymal cells through the transfer of EVs IGF-2 and IGFBP2." (PMID 38037077, 2023). "However, whether the IGF2–IR-A axis elicits a role in cancer metabolic reprogramming is not established." (PMID 31480557, 2019). "However, the role of IGF2 epigenetic regulation in cancer stem cells has not been elucidated." (PMID 27275535, 2016).
cancer (continued). "CXCL12, known to be induced by IGF2 and to promote immune suppression, overlapped with IGF1 expression rather than IGF2 in ESCC, suggesting a possible link between interCAFs IGF signaling and immunomodulation in this cancer." (PMID 41228323, 2025). "For example, CAFs secrete epidermal growth factor (EGF), insulin-like growth factor 2 (IGF2), and fibroblast growth factor 4 (FGF4), which increase not only the proliferation but also the survival of cancer cells after irradiation." (PMID 34135469, 2021). "Although IGF2 and IGF2R genes were also observed to be related to cancer, they were not the best biomarkers specifically using our QCIGISH method." (PMID 32448196, 2020). "On the other hand, several cancer genes, notably IGF2BP3, IGF2, and LIPG, do not produce chimeras but are consistently upregulated by geneUIB fusions." (PMID 32631391, 2020). "The connections between IGF2 and type II diabetes mellitus (T2DM) and non-islet cell tumor hypoglycemia (NICTH) in etiology of this cancer are also examined." (PMID 31623387, 2019). "Insulin-like growth factor II (IGF2) is maternally imprinted in most tissues, but the epigenetic regulation of the gene in cancer stem cells (CSCs) has not been defined." (PMID 27275535, 2016). "Thus, an attractive hypothesis is that increased epithelial IGF-2 production leads to macrophage and fibroblast chemotaxis, which subsequently stimulates CXCL8 expression in stromal cells through the IG-F2/IGF-2R axis, resulting in endothelial cell recruitment and cancer cell migration." (PMID 26465273, 2015). "For IGF2, LOI was observed in normal solid tissues, but the prevalence did not increase in cancer." (PMID 39199324, 2024). "It should be considered, however, that the inconsistency of the methylation changes of the imprinted loci outside of 11p15.5 suggests that apart from H19/IGF2 and KCNQ1OT1/CDKN1C, the other imprinted genes do not likely act as drivers of cancer progression in WT." (PMID 33217932, 2020). "In contrast to our analysis, a prior model of this system in cartilage suggested the IGF2R might play a role in regulating IGF2 interactions with IGF1R; however, these findings were not confirmed experimentally and were not seen in our model utilizing data from cancer cells." (PMID 26861122, 2016).
metabolic disorders (23 papers, 2013 to 2025). "Beyond its metabolic functions, IGF2 is a potent mitogen, influencing cell proliferation, differentiation, and organogenesis, which may explain why its dysregulation is often implicated in oncogenic processes as well as metabolic disorders." (PMID 40566344, 2025). "Studies have consistently demonstrated that PFAS compounds can induce changes in DNA methylation at imprinted loci such as IGF2 and MEST, thereby influencing fetal growth trajectories and increasing susceptibility to metabolic disorders." (PMID 40566344, 2025). "miR-877-5p functions as an oncogenic miRNA in TNBC and metabolic disorders by targeting genes such as IGF2 and TIMP3, promoting proliferation and invasion." (PMID 41009685, 2025). "Insulin-like growth factor 2, a member of the insulin family, plays an important role in embryonic development, metabolic disorders, and tumorigenesis by combining with three receptors with different degrees of affinity." (PMID 36358907, 2022). "IGF-2 is strongly expressed in the central nervous system (CNS) and exerts various functions in brain development, neurological disorders, and metabolic diseases." (PMID 32012199, 2020). "The aim of this study was to clarify the alteration in methylation levels at differentially methylated regions (DMRs) of GNAS and IGF2 in fetuses of GDM women and to explore the possible mechanisms linking maternal GDM with high risk of metabolic diseases in later life of GDM offspring." (PMID 25269528, 2014). "Insulin-like growth factor 2 (IGF2) is a part of the insulin group and has an influence on metabolic disorder development." (PMID 38068941, 2023). "Placental CDKN1C, PHLDA2 and IGF-2 levels monitoring may be useful for prediction and prevention of the development of SGA births and its related postnatal metabolic diseases." (PMID 31194812, 2019). "The multifaceted effects of IGF2 and methylation plasticity of its DMR have led many, including our group, to study how diverse early-life environmental conditions influence methylation of this region and its subsequent relations to many metabolic disorders." (PMID 31182144, 2019).
infection (19 papers, 2004 to 2025). The state of being infected such as from the introduction of a foreign agent such as serum, vaccine, antigenic substance or organism. "RRM2 and insulin-like growth factor-2 messenger ribonucleic acid (mRNA)-binding protein 3 (IGF2BP3) gene knockdown was achieved by infection with lentiviruses." (PMID 38820515, 2024). "We took advantage of the MTE4-14 cell line to investigate the effect of the CV-B4 infection on the Igf2 expression." (PMID 33672010, 2021). "Results show that in utero infection by CV-B4 induces a significant decrease in Igf2 and Myo7 expression at both mRNA and protein level in whole thymus and in enriched TECs as well." (PMID 34361972, 2021). "Among Igf2 mRNA transcripts, Igf2 V3 and Igf2 V1, the major and minor transcripts, respectively, were strongly downregulated during the CV-B4 infection." (PMID 33672010, 2021). "The infection induced a dramatic decrease in Igf2 transcripts and IGF-2 production in long-term cultures of this cell line." (PMID 32150956, 2020). "Others proved that infection of IGF2 LOI cell lines with Ad312-E1A reduced cell viability and induced their apoptosis." (PMID 31623387, 2019). "We further examined apoptosis in all cell lines with varied IGF2 imprinting using flow cytometry at 72 h after infection." (PMID 23171475, 2012). "Moreover, IGF2 secretion was significantly increased upon rHSVQ infection while IGF1 was unaffected as confirmed by ELISA." (PMID 38853689, 2024). "In this model, the total Igf2 mRNA level was decreased following CV-B4 infection." (PMID 33672010, 2021). "Therefore, the Igf2 P3 promoter region −68 to −22 is targeted and downregulated during CV-B4 infection." (PMID 33672010, 2021). "In conclusion, these findings shed new light on the thymic IGF2 regulation by CV-B4 infection, thus strengthening the hypothesis of a possible role of CV-B infections in decreasing central tolerance to insulin." (PMID 33672010, 2021). "Furthermore, the infection with CVB4 resulted in a decreased activity in two regions of the core promoter of IGF2 transcript V3." (PMID 34072590, 2021). "The main discoveries of this study are the following: first, in the thymic epithelial MTE4-14 cell line, CV-B4 infection decreased the transcriptional activity of the murine Igf2 P3 promoter together with Igf2 V3 and V1 mRNA, which resulted in the decrease in the pro-IGF2 level." (PMID 33672010, 2021). "In addition, a significant interaction effect on claudin-1, IGF-2 and mucin-2 mRNA expressions occurred between NE infection and BLJ addition." (PMID 32110391, 2020). "Moreover, CV-B4 infection of a murine mTEC line induces a marked decrease in Igf2 transcription and IGF-2 production." (PMID 26175734, 2015). "Through the inhibition of Igf2 expression in TECs, CV-B4 infection could lead to a breakdown of central immune tolerance to the insulin family and promote an autoimmune response against insulin-secreting islet β cells." (PMID 26175734, 2015). "To gain insight into the mechanism(s) whereby SYT-SSX might induce IGF2 in different hMSC populations, we compared the DNA methylation status twelve days following infection with SYT-SSX1 or empty vector." (PMID 19936258, 2009). "To determine whether over expression of igf2 would affect disassembly of virions, we examined the fate of virus during the first hours of infection." (PMID 15333144, 2004).
infection (continued). "Therefore, infections with CVB4 can modulate the expression of thymic IGF2, which strengthens the hypothesis of a possible role of CVB infections in decreasing central tolerance to insulin." (PMID 34072590, 2021). "The effect of an acute infection of TEC cells (MTE4-14 cells line) by CVB4 on IGF2 transcripts and upstream signaling events impacting IGF2 regulation was recently reported by our team." (PMID 34072590, 2021). "Our results also indicate that the two promoter regions of Igf2 P3, −68/−22 and −168/−116 (both relative to the TSS), were negatively regulated during the CV-B4 infection." (PMID 33672010, 2021). "During the CV-B4 infection (MOI = 0.05), RT-qPCR results showed a gradual decrease in total Igf2 levels on day 2 and 3 P.I.." (PMID 33672010, 2021). "Previous data from the same authors showed that infection with Ad-DT-A resulted in growth inhibition (75.4 ± 6.4%) and increased the percentage of apoptosis (20.8 ± 5.9%) in human CRC HCT-8 cell line (IGF2 LOI) compared with control group." (PMID 31623387, 2019). "However, it has not been determined which are the Igf2 transcripts and promoters modulated and which are the contributing factors affecting the decrease in Igf2 mRNA expression in TECs following infection with CV-B4." (PMID 33672010, 2021). "Similar to our results, a downregulation of IGF2 expression in enriched TECs of mice following CV-B4 infection was observed, despite the absence of a proof of infection of those cells, which raises this hypothesis." (PMID 34361972, 2021). "Both wild-type HSV and rQNestin34.5v.1 significantly increased the expression of IGF2, but not IGF1, indicating that up-regulation of IGF ligands by oHSV infection is limited to IGF2 regardless of the virus type." (PMID 38853689, 2024). "Moreover, our results revealed that NE infection upregulated the mRNA levels of the growth factors TGF-β3 and IGF-2 while reducing the levels of TLR-signaling-pathway negative regulator A20 in the jejunum compared with the non-infected groups." (PMID 31311959, 2019).